MCAM (melanoma cell adhesion molecule)
Diseases named in the same sentence as MCAM in open-access papers (continued):
Sharing a sentence is not in itself a finding about the gene and the disease.
tumor (continued). "Other studies have linked expression of MCAM on tumor cells to their metastatic potential." (PMID 22792325, 2012). "Besides, the presence of MCAM+ ECs in metastatic lymph nodes (MLNs) was confirmed by scRNA sequencing and spatial transcriptomics, and these cells were found to be closely associated with tumor cells." (PMID 40221534, 2025). "Anti-MCAM antibodies are potent therapeutic agents with various mechanisms of action, including direct tumor inhibition, immune activation, and antiangiogenic effects." (PMID 41388158, 2025). "Early FDIM showed upregulation of genes linked to tumour initiation, immune recruitment, and motility (e.g., STOX1, PEG3, XIAP, MCAM, VIM)." (PMID 40683913, 2025). "MCAM binds various cellular surface receptors or co-receptors to trigger signal transduction, cell proliferation and motility, tumor angiogenesis, and tumor cell metastasis." (PMID 40878909, 2025). "As a prominent example of a cell adhesion molecule of the immunoglobulin superfamily, the melanoma cell adhesion molecule (MCAM) has been described to drive tumour progression in multiple cancer types." (PMID 39945026, 2025). "Preclinical studies using anti-MCAM antibodies show promising results in reducing tumor growth, metastasis, and resistance to existing therapies." (PMID 41388158, 2025). "In GC, MCAM expression is upregulated, and its levels are positively correlated with tumor aggressiveness, lymph node metastasis, and overall poor patient outcomes." (PMID 40924339, 2025). "Significantly inhibited angiogenesis and tumor growth and metastasis were also observed when anti-MCAM antibody AA98 was used in combination with vorinostat, which is a histone deacetylase inhibitor." (PMID 41388158, 2025). "The IHC analysis showed distinct membranous and partial cytoplasmic staining in tumor epithelial cells, suggesting an upregulation of MCAM during the intermediate stages of cancer progression." (PMID 40924339, 2025). "Therapeutic targeting of MCAM with the mAb AA98 significantly inhibited tumor growth in both malignant organoid PT and PT patient-derived xenograft (PDX) models." (PMID 41388158, 2025). "CTCs can be identified by markers like melanoma-associated antigen 3 (MAGE-A3), melanoma cell adhesion molecule (MCAM), melan-A, and chondroitin sulfate proteoglycan (MCSP), which can provide insights into tumor progression and metastatic potential." (PMID 40002300, 2025). "Melanoma Cell Adhesion Molecule (MCAM, also known as CD146), originally identified as an endothelial marker linked to angiogenesis during tumor progression, is widely expressed throughout the vascular system." (PMID 40221534, 2025). "MCAM has emerged as a key player in cancer biology, influencing multiple aspects of tumor progression, including epithelial-mesenchymal transition, angiogenesis, metastasis, and therapy resistance." (PMID 41388158, 2025). "MCAM’s dual role as a cell adhesion molecule and a signaling receptor makes its functional output highly dependent on the tumor microenvironment." (PMID 41388158, 2025). "Anti-MCAM antibodies can be combined with other agents to increase therapeutic sensitivity and combine both the anti-angiogenic and anti-tumor properties of antibodies." (PMID 41388158, 2025). "Both its membrane-bound and soluble forms contribute to aggressive cancer phenotypes, with s-MCAM acting as a potent enhancer of tumor survival and dissemination." (PMID 41388158, 2025). "Next, we investigated the efficacy of anti-MCAM-CAR-NK cells in limiting NB xenograft tumor growth in vivo in NB (SK-N-FI)-xenografted NSG (NOD.Cg-Prkdcscid Il2rgtm1Wjl/SzJ) mice." (PMID 39554906, 2024). "Focusing on CAFs, our analysis revealed a novel subpopulation marked by CD34+PI16+, which gave rise to the classical ACTA2+MCAM+ CAFs in tumor, also known as myCAF (data unpublished)." (PMID 39401181, 2024). "Anti-MCAM-CAR-NK cell treatment significantly decreased tumor growth and prolonged animal survival in an NB xenograft mouse model." (PMID 39554906, 2024).
tumor (continued). "Immunohistochemical studies showed the co-expression of macrophage markers (CD163, CD68) and pericyte markers (NG2, MCAM) in perivascular regions of the tumor." (PMID 39796646, 2024). "In agreement with our transcriptional analysis, immunofluorescent staining of healthy livers revealed an enrichment of MCAM+ GFP+ cells surrounding blood vessel-like structures, while MCAM+ GFP+ cells were only sparely found within metastatic tumours." (PMID 38678021, 2024). "The melanoma cell adhesion molecule, shed from endothelial and cancer cells, is a soluble growth factor that induces tumor angiogenesis and growth." (PMID 38137406, 2023). "This inhibitory activity is reflected by a reduction in MCAM gene expression and increased promoter methylation in tumour tissue compared to normal breast tissue." (PMID 37138793, 2023). "Single cell transcriptome data revealed MCAM expression in multiple cell types, including the malignant cells, tumour vasculature and normal epithelium." (PMID 37138793, 2023). "Strikingly, elevated MCAM expression is found in the CMS4 angiogenic tumor subtypes and advanced-stage disease (i.e., stages 3 and 4)." (PMID 38137406, 2023). "The soluble form of the melanoma cell adhesion molecule (sMCAM, sMUC18, or sCD146) has been reported as a novel promoter of tumor angiogenesis and tumor growth in experimental melanoma, ovarian and pancreatic cancers." (PMID 38137406, 2023). "For instance, MCAM overexpression promotes tumor cell migration, tumor invasion, and cancer stem cell‐like activities in triple‐negative breast cancer." (PMID 34961985, 2022). "In agreement, our findings showed higher expression of MCAM in tumor samples from OS patients who had metastases within 5 years compared to those without metastasis." (PMID 34961985, 2022). "MCAM expression was markedly reinforced in OS tumor samples in comparison to normal samples, as well as in OS cells (Saos-2 and SW1353) in comparison to hFOB1.19 cells." (PMID 36340580, 2022). "We identified 12 markers for LUAD3, including DCBLD2, MCAM and VIM, which are considered EMT markers that are usually associated with tumor dedifferentiation and poor prognosis in NSCLC44–46." (PMID 35383171, 2022). "Another radiolabeled anti‐MCAM antibody was used to target circulating and metastatic tumor cells in an OS mice model." (PMID 34961985, 2022). "The levels of the melanoma cell adhesion molecule MCAM (MUC18/MelCAM/CD146) are also correlated with tumor aggressiveness." (PMID 35974375, 2022). "Specifically, three membrane‐bound MUCINs (MUC3A, MUC12, and MUC20) and one atypical mucin (MCAM) were overexpressed in the tumor samples (p < 0.05)." (PMID 34327857, 2021). "Another important surface biomarker, melanoma cell adhesion molecule (MCAM), also called CD146, is a known tumor suppressor." (PMID 33499047, 2021). "MCAM shows pro-angiogenic potential: it is a membrane signal receptor in tumor-induced angiogenesis and has been identified as a novel target for anti-angiogenic agents in anticancer therapy." (PMID 32042281, 2020). "The atypical mucins mRNA (MUC14/EMCN and MUC18/MCAM) were also increased in tumor samples (p < 0.01)." (PMID 33182511, 2020). "This is in line with a recent report that identified melanoma cell‐adhesion molecule (MCAM)/CD146 expression in tumor vessels as a prognostic marker for poor outcome in RCC." (PMID 31880322, 2020). "The HEK293 cell line exhibits a high endogenous level of MCAM, comparable to that of several tumour cell types, and was thus selected for use in functional experiments of this investigation." (PMID 28589943, 2017). "In particular, in this study, sCD146/MCAM/MUC18 secreted by CD146-positive tumours does not only display effects on tumour angiogenesis but also on tumour growth and survival." (PMID 28280601, 2017).
tumor (continued). "CD146, also named MUC18 or MCAM, is associated with tumor progression in several of the mentioned cancers, and has been shown to act as a receptor in promotion of angiogenesis and vascular development." (PMID 27776176, 2016). "Overall, these results demonstrate that MCAM plays a role in both cell–cell interactions and signal transduction in tumor cells." (PMID 26703751, 2015). "Later studies found that MCAM is overexpressed in most malignant and metastatic cancer and plays a significant role in tumor progression." (PMID 26703751, 2015). "Nevertheless, it should be noted that MCAM has been previously found to be expressed on haematopoietic cells and tumor cells, where it plays a role in the interaction with vascular endothelial cells." (PMID 24058540, 2013). "We further sought to validate the expression of two adhesion molecules at the protein level using flow cytometry: CEACAM1, a tumor marker and broad inhibitor of T-cell function and MCAM, a Th17 marker and regulator of cell recruitment into the brain." (PMID 24359430, 2013). "The fact that MCAM plays different roles in different tumours reflects the complexity of cancer molecular biology." (PMID 22610942, 2012). "Previous research showed that abnormal expression of MCAM occurs in a variety of tumours and is related to tumour development." (PMID 22610942, 2012). "In general, the inhibition of MCAM leads to a change in interaction among tumour cells and between tumour cells and the extracellular matrix, leading to the alterations in cancer invasion, metastasis and apoptosis." (PMID 22610942, 2012). "In combination, the strongest pair is APC and MCAM, showing 78.3% frequency in tumours and 23.3% in normals." (PMID 22068818, 2012). "Moreover, MCAM+ ECs were found adjacent to osteoblasts, suggesting potential cell-cell interactions between MCAM+ ECs and tumor cells." (PMID 40221534, 2025). "To further dissect the role of MCAM on the tumour‐cell intrinsic metastatic potential or the impact of MCAM on immune evasion during metastatic dissemination, we intradermally transplanted HCmel12 CRISPR control and HCmel12 MCAM knockout cells in NOD/SCID mice." (PMID 39945026, 2025). "MCAM has also been described in the context of the tumor microenvironment." (PMID 41388158, 2025). "Furthermore, long non-coding RNA (lncRNA) uc001pwg. has been found to upregulate MCAM expression in endothelial cells derived from human-induced pluripotent stem cells (hiPSCs), suggesting a role in vascular development and possibly tumor angiogenesis." (PMID 41388158, 2025). "Moreover, elevated MCAM expression increased with advancing T stage (tumor invasion depth), with significantly higher levels observed in T3–T4 tumors compared to T1–T2 (p = 0.001)." (PMID 40924339, 2025). "It was shown that MCAM expression is strongly associated with high tumor grade, negative ER and PR, and TNBC in patient samples." (PMID 41388158, 2025). "MCAM function may shift during cancer progression, acting as a tumor suppressor in early stages but promoting metastasis in advanced disease." (PMID 41388158, 2025). "High MCAM expression in EC and PVC might account for the poor prognosis of patients with high MCAM gene expression levels, reflecting greater vascularisation of certain tumours." (PMID 37138793, 2023). "The involvement of MCAM during tumor development and angiogenesis has already been studied." (PMID 38137406, 2023). "To determine if the anti-tumor effect of anti-sMCAM mAb treatment was dependent on MCAM expression by the tumor cells themselves or by the host, we treated immunodeficient NSG mice bearing either human DLD1 (mMCAM-positive) or LoVo (mMCAM-negative) CRC tumors with anti-sMCAM mAb." (PMID 38137406, 2023). "Furthermore, we found that high tumor NOX1 mRNA expression was associated with WT KRAS while both low ADAM17 and MCAM mRNA expression was associated with mutated KRAS." (PMID 38137406, 2023).
tumor (continued). "However, our approach was different and we determined MCAM gene expression in cells and tumours based on their sEMT; this approach reveals that MCAM expression is highest in the more mesenchymal cells/tumours." (PMID 37138793, 2023). "MCAM plays an important role in cell adhesion, especially in enhancing hematogenous tumor spread." (PMID 36443669, 2022). "By analyzing the tumors, we discovered that catulin reporter system marks not only invasive cancer cells enriched at the tumor-stroma border and around newly formed vasculature but also rare population of highly plastic MCAM positive cancer cells that participate in vascular mimicry." (PMID 35879327, 2022). "In addition, wound healing tests and GSEA results from the RNA‐Seq data of si‐MCAM‐transfected OS cells confirmed that the MCAM gene mediated the wound healing process in tumor cells." (PMID 34961985, 2022). "We reanalyzed only tumor samples (excluding cells from normal controls), and within these samples analyzed all the cells that were defined as “fibroblasts” or “stellate cells” in the original dataset, and excluded MCAM positive cells (a pericyte marker)." (PMID 36316305, 2022). "Interestingly, 5HT2B and MCAM expression coincided in various tumours (PUM5, 6, 10 and 9) and within areas of the tumours." (PMID 34885099, 2021). "For example, heterogeneous MCAM expression in UM described in a previous report may have contributed to the lower proportion of MCAM-expressing tumours identified in the present study." (PMID 34885099, 2021). "Other markers such as 5HT2B (1.1 ± 0.2), MCAM (1.6 ± 0.5) and RANK (1.3 ± 0.4) exhibited moderate levels of predominantly membrane-associated expression and were expressed in a lower proportion of tumour samples." (PMID 34885099, 2021). "CD146 was originally acknowledged as a tumor marker for melanoma (MCAM)." (PMID 32793232, 2020). "The silencing of MCAM potentiated the effect of irradiation (IR) in both tumor models." (PMID 32204304, 2020). "However, the combination with therapeutic shRNA molecule against MCAM resulted in a higher number of tumor cures (27%) compared to the combination with control plasmid pControl (8%)." (PMID 32204304, 2020). "On the contrary, MUC18/MCAM staining was only observed in the stroma surrounding the tumor cells." (PMID 33182511, 2020). "Therefore, it would be reasonable to specifically target the MCAM expressed on tumor cells, which has already been performed by the development of antibodies recognizing only MCAM expressed in tumor cells." (PMID 32204304, 2020). "Thus sCD146/MCAM/MUC18 induces the expression of either proteins involved in tumour proliferation and invasion or proteins inhibiting apoptosis and senescence." (PMID 28280601, 2017). "Laminin, known to promote cancer progression, may enhance tumor cell migration through activation of MCAM, IQGAP1 recruitment and subsequently myosin II retraction." (PMID 29240845, 2017). "However, it has been reported that tumor vessels also highly express melanoma cell adhesion molecule (CD146), a member of the immunoglobulin gene superfamily." (PMID 25997612, 2015). "Thus, MCAM played a dynamic role for tumor cells migrating in synthetic ECM, and was a prominent feature on the uropod-like structure for rounded and elongated migration modes." (PMID 24349113, 2013). "However, the MCAM-positive tumour rate significantly increased in borderline ovarian tumours and malignant epithelial ovarian tumours, suggesting that MCAM expression is correlated with tumour malignancy." (PMID 22610942, 2012). "The specific molecular mechanisms by which MCAM affects tumour growth are not yet fully understood." (PMID 22610942, 2012). "MCAM, ALCAM, NCAM, and L1CAM have all been implicated in the formation of large cell aggregates and have been shown to increase the metastatic capability of tumour cells." (PMID 22272201, 2012).
tumor (continued). "Although a report suggests that MCAM expression on tumor cells decreases the adhesion of the cells to laminin, the composition of the laminin in that study is unclear, and may have lacked the laminin 411 isoform." (PMID 22792325, 2012). "Anti-MCAM antibodies can directly bind to these tumor cells and could induce apoptosis." (PMID 41388158, 2025). "This suggests that MCAM could be an effective target in anticancer therapies aimed at inhibiting angiogenesis, particularly since its inhibition or knockdown reduces the adhesion, migration, and proliferation of tumor cells." (PMID 41388158, 2025). "Additionally, MCAM is critically involved in tumor aggressiveness, metastasis, and poor prognosis." (PMID 40221534, 2025). "Moreover, continuous EGFR-TKI treatment induced the upregulation of MCAM expression in tumours." (PMID 40713600, 2025). "Given that MCAM is mainly expressed by tumor cells and endothelial cells, the lower MCAM transcription levels in ghM compared to skin may be explained by the poor vascularization of the encapsulated ghMs included in the study compared to the normal-skin controls, which were well vascularized." (PMID 40724880, 2025). "Moreover, after injecting cells expressing catulin reporter into immunocompromised mice, the catulin reporter system marked invading cancer cells at the tumor border and the cells around newly generated vasculature as well as the small population of MCAM-positive cells participating in VM." (PMID 38372877, 2024). "Finally, a fucosyltransferase inhibitor repressed the fucosylation modification of MCAM, promoting cell proliferation, invasion and tumor metastasis in Fut2-overexpression cells, indicating that fucosylation of MCAM might be a mediator of Fut2 in CRC." (PMID 36739428, 2023). "Owing to the widespread involvement of MCAM in various aspects of tumor development, drugs targeting MCAM are promising and meaningful, as they may act from multiple perspectives rather than on a specific aspect of tumors, potentially having strong antitumor effects." (PMID 37701037, 2023). "Thus, if tumour cells in the vasculature are present as a group (e.g., via collective migration), it is possible that cell-cell interactions mediated by MCAM may upregulate FAK and protect the cells from anoikis." (PMID 22272201, 2012). "In cervical cancer, the anti- MCAM monoclonal antibody AA98 enhanced radiosensitivity, promoting apoptosis and reducing tumor cell survival." (PMID 41388158, 2025). "Proteins downregulated in KO tumours with roles in regulating adhesion and angiogenesis included EphA2, integrin ITGB5, MCAM, and MYLK (myosin light chain kinase)." (PMID 41226720, 2025). "Such dedifferentiated PSMC (dPSMC) were apparent within strands of stromal tissue between tumour glands with disorganised isolated PSMC displaying decreased CNN1, CCDC102B and MCAM immunopositivity." (PMID 41378308, 2025). "This enhanced colony formation was attenuated by S100A8/A9 antibody treatment in both the MCAM WT and MCAM DN groups, further supporting the involvement of S100A8/A9 in MCAM-mediated tumor-promoting effects." (PMID 40924339, 2025). "Conversely, a study indicated that downregulation of MCAM significantly suppressed EMT activity, leading to obviously weakened tumour growth and distant metastasis of BRCA." (PMID 40778650, 2025). "MCAM interaction with galectin-3 triggers the activation of the AKT pathway, thereby enhancing tumor cell survival, invasiveness, and the secretion of metastasis-promoting cytokines." (PMID 41388158, 2025). "MCAM, originally identified as CD146, is a cell adhesion molecule involved in various tumor physiological activities including angiogenesis, immune response, and migration." (PMID 37701037, 2023). "Previous studies have found that the expression levels of MUCINs, including MUC1, MUC4, MUC12, MUC13, MCAM, and LAMA4 were correlated with poor survival of ccRCC patients, and/or promotion of tumor cell proliferation in vitro." (PMID 34327857, 2021).